CDC42EP1 (CDC42 effector protein 1)
Description:
Probably involved in the organization of the actin cytoskeleton. Induced membrane extensions in fibroblasts.
Synonyms: BORG5; CEP1; MSE55
Tractability: Antibody: UniProt places it where antibodies can reach, with high confidence; its Gene Ontology location is reachable by antibodies, with medium confidence; the Human Protein Atlas places it where antibodies can reach. PROTAC: ubiquitination databases record sites on it; its protein half-life has been measured.
Gene: Protein-coding gene on chromosome 22 (37,555,112 to 37,569,764, forward strand). Ensembl gene ENSG00000128283.
Subcellular location: Endomembrane system; Cytoplasm, cytoskeleton
Subcellular location (Human Protein Atlas): Plasma membrane; Actin filaments; Nucleoplasm
Pathways (Reactome):
Signal Transduction: CDC42 GTPase cycle; RAC1 GTPase cycle; RAC2 GTPase cycle; RAC3 GTPase cycle; RHOG GTPase cycle; RHOJ GTPase cycle; RHOQ GTPase cycle
Gene Ontology:
Molecular function: cadherin binding involved in cell-cell adhesion; protein binding; small GTPase binding
Biological process: positive regulation of pseudopodium assembly; regulation of cell shape; positive regulation of actin filament polymerization; Rho protein signal transduction; cell-cell adhesion
Cellular component: actin cytoskeleton; adherens junction; focal adhesion; plasma membrane; cytoplasm; cytoskeleton; cytosol; endomembrane system
Genetic constraint (gnomAD): Loss-of-function variants: 11 observed, 8.67 expected, observed/expected ratio (o/e) 1.27, 90% interval 0.79 to 1.86. That is too few expected variants to judge how well the gene tolerates losing a copy. Missense variants: 556 observed, 504.67 expected, observed/expected ratio (o/e) 1.1, 90% interval 1.03 to 1.18. Synonymous variants: 230 observed, 212.86 expected, observed/expected ratio (o/e) 1.08, 90% interval 0.97 to 1.21.
Homologues: Orthologues: chimpanzee CDC42EP1 (99% identical), macaque CDC42EP1 (93% identical), pig CDC42EP1 (78% identical), dog CDC42EP1 (75% identical), guinea pig CDC42EP1 (75% identical), mouse Cdc42ep1 (75% identical), rat Cdc42ep1 (73% identical), rabbit CDC42EP1 (64% identical), zebrafish cdc42ep1a (31% identical), zebrafish cdc42ep1b (30% identical), tropical clawed frog cdc42ep1 (24% identical). Paralogues in human: CDC42EP4 (24% identical), CDC42EP3 (16% identical), CDC42EP2 (15% identical), CDC42EP5 (15% identical), C15orf62 (11% identical).
Diseases named in the same sentence as CDC42EP1 in open-access papers:
CDC42EP1 is named in the same sentence as 2 diseases in open-access papers, as found by Europe PMC text mining. Sharing a sentence is not in itself a finding about the gene and the disease. The quoted sentences say what the papers report.
cancer (5 papers, 2012 to 2024). A tumor composed of atypical neoplastic, often pleomorphic cells that invade other tissues. "Eight of nine specimens withATXN1 mutations were associated with advanced-stage disease,suggesting involvement in epithelial-mesenchymal transition and cancer metastasis.CDC42EP1, a member of the Rho GTPase family, represents a novelplayer in cancer development, particularly in OTSCC." (PMID 39116405, 2024). "Berberine also showed anti-metastatic properties in several cancer cell lines, acting on 72 kDa type IV collagenase (MMP2), Cdc42 effector protein 1 (CDC42EP1), and ras-related C3 botulinum toxin substrate 1 (RAC1), transforming protein RhoA (RHOA) and urokinase-plasminogen activator A (PLAU)." (PMID 23213296, 2012).
CDC42EP1 also shares sentences with these, for which no sentence is quoted: melanoma (1 paper).